BRCA1 (BRCA1 DNA repair associated)
Diseases named in the same sentence as BRCA1 in open-access papers (continued):
Sharing a sentence is not in itself a finding about the gene and the disease.
breast cancer (continued). "eTable 4 in the Supplement suggests that pathogenic variants in BRCA1 were associated with earlier age at diagnosis of female breast cancer (−5.7 years)." (PMID 35420638, 2022). "Women carrying a pathogenic variant (pV) in BRCA1/2 face elevated lifetime risks for breast cancer (BC), contralateral BC, and ovarian cancer (OC)." (PMID 36011268, 2022). "Clinical trials using PARP inhibitors for breast cancer with germline BRCA1/2 mutations have shown promising results in the neoadjuvant and metastatic setting, and are being actively studied in TNBC with HRDs." (PMID 34071012, 2021). "The high-risk breast cancer susceptibility genes BRCA1 and BRCA2 account for up to 30% of these hereditary cases, which leaves a large proportion of familial clustering unexplained." (PMID 33468213, 2021). "Younger age, triple-negative subtype, and number of breast cancer cases in the family were highly correlated with the presence of a BRCA1 pathogenic variant." (PMID 35155181, 2021). "UBE2T modulates breast cancer progression by interacting with the BRCA1 DNA repair-associated/BRCA1-associated RING domain 1 complex." (PMID 34199813, 2021). "The first study on breast cancer risk was a case-control study including 1054 pairs of women with BRCA1 mutation and 326 pairs of women with BRCA2 mutation." (PMID 33996049, 2021). "Because BRCA1/2 mutations are the most common CPGs altered in breast cancer, yet such mutations have thus far proven to be directly non-druggable, there is a significant need for the development of alternative therapeutic approach for these cancers." (PMID 34070674, 2021). "In 15–20% of ovarian cancer patients, a mutation in the tumor suppressor genes breast cancer 1/2 (BRCA1/2) can be found, leading to a familial accumulation of ovarian and breast cancer." (PMID 34571986, 2021). "In agreement with previous studies, carriers of BRCA1/2 mutations in the current study are characterized by early onset, positive family history of breast cancer, premenopausal state at diagnosis, and positive lymph node involvement." (PMID 34206661, 2021). "The breast cancer susceptibility factors BRCA1 (FANCS) and BRCA2 (FANCD1) are key players in homologous recombination and act downstream of the FANCI/FANCD2 complex to repair the DSBs formed by ICLs processing." (PMID 34359655, 2021). "In breast cancer, reduced BRCA1 expression or mutation leads to accumulation of phosphorylated Akt (pAkt)." (PMID 34638302, 2021). "Breast cancer susceptibility genes 1 and 2 (BRCA1, BRCA2) are independent tumor suppressor genes (TSG) working in concert to protect the genome against mutations." (PMID 33391401, 2021). "As previously shown, our systematic analysis confirms that the major susceptibility gene for breast cancer BRCA1 is under strong positive selection." (PMID 33441416, 2021). "Can patients with breast cancer who carry a BRCA1/2 variant safely undergo breast-conserving therapy (BCT)?" (PMID 33890992, 2021). "Women who inherit a deleterious germline BRCA1 or BRCA2 mutation face high lifetime risks of developing breast cancer by the age of 80, which are estimated to be 72% and 69%, respectively." (PMID 34828379, 2021). "BRCA1/2 pathogenic variants demonstrate high penetrance with approximately 50–90% lifetime risk of breast cancer." (PMID 33507482, 2021). "Testing positive for a pathogenic BRCA1 or BRCA2 variant indicates a cumulative breast cancer risk, up to the age of 80, of 72% and 69%, respectively." (PMID 34069035, 2021). "Effects of media conditioned by normal ADSCs showed largely comparable effects on BRCA1-mutated and wildtype breast cancer cell lines thus advocating lipofilling, preferentially employing allogeneic non-mutated ADSCs." (PMID 34228231, 2021).
breast cancer (continued). "In cancers with strong RS such as breast cancer with the BRCA1/2 mutation, targeting these two different fork stabilizing mechanisms by the combination of PARPi and ATRi would lead to increased DNA ds-breaks and tumor cell death." (PMID 34439286, 2021). "DNA aberrant hypermethylation was observed to be the major cause of transcriptional silencing of the BRCA1 gene, a phenomenon ranging from 13% to 40% in sporadic breast cancer." (PMID 33808555, 2021). "Overall, these data implicate increased cyclin E1 protein stability, rather than gene amplification, as the cause for high cyclin E1 levels observed in BRCA1 mutated breast cancer." (PMID 34465787, 2021). "Bilateral breast cancer is one of the risk-enrichment criteria for BRCA1/2 mutation in the Pen II risk model, BRCAPRO, and NCCN guidelines to select appropriate patients indicated for germline mutation testing." (PMID 34574977, 2021). "The link between BRCA1/2 mutations and high susceptibility to breast cancer development has been well-established for years." (PMID 33540843, 2021). "The cumulative 10-year risk of developing contralateral breast cancer in this cohort was 25%, 95% CI (23.5–26.4%) and 18.8%, 95% CI (17.1–20.5%) for BRCA1 and BRCA2 heterozygotes, respectively." (PMID 34113011, 2021). "In this context, it was shown that breast cancer participants with the BRCA1 mutation presented a higher degree of oxidative damage to lipids (8-isoprostane and MDA) but not AOPP in the saliva." (PMID 34326920, 2021). "To address this ambiguity, we sought to elucidate the impact of BRCA1/2 mutation carriership on long-term clinical outcomes for the first time in Egyptian female breast cancer patients." (PMID 34206661, 2021). "Two to three percent of breast cancer patients harbor germline mutation of either BRCA1 or BRCA2 genes." (PMID 34439286, 2021). "BRCA1 promoter methylation was more frequent in invasive than in in situ carcinomas and also was positively associated with mortality in breast cancer." (PMID 33970384, 2021). "To determine if Gata3 affects Brca1 deficient mammary tumor metastasis, we transplanted Empty- and Gata3-expressing p18-/-; Brca1MGKO tumor cells into MFPs of NSG mice." (PMID 34373738, 2021). "In this study, we explored the inter- and intra-tumor heterogeneity of BRCA1 deficient mouse mammary tumors." (PMID 34815798, 2021). "Upregulation of HIF1A in BRCA1-deficient fibroblasts has previously been shown to drive breast cancer growth." (PMID 33898308, 2021). "For example, BRCA1/2 mutations in breast cancer (BC) are uniquely associated with the upregulation of genes located in the right part of the map." (PMID 33525353, 2021). "In a series of high-risk families, 10%-16% of men with breast cancer are found to have BRCA1 mutation." (PMID 35036180, 2021). "In the present study, we prospectively evaluate the relationship between total arsenic levels, measured in whole blood, and breast cancer risk among women carrying mutations in BRCA1." (PMID 34283078, 2021). "Poly (ADP-ribose)-polymerase inhibitors (PARPi) are of particular interest in treating hereditary breast cancers occurring in patients with germline BRCA1/2 (gBRCA1/2) mutations." (PMID 34680491, 2021). "The American Cancer Society guidelines recommend MRI-based screening not only for BRCA1/2-positive women but also for those with a lifetime risk of greater than 20% for developing breast cancer." (PMID 33492646, 2021). "This study comprised 103 Egyptian female breast cancer patients previously tested for BRCA1/2 mutations." (PMID 34206661, 2021). "Published experiments demonstrated that downregulation of EMI1 in BRCA1-deficient breast cancer cells led to a decrease in sensitivity of the cells to PARPi." (PMID 33412559, 2021).
breast cancer (continued). "BRCA1 (for Breast Cancer 1) was shown to down regulate β-hCG expression in breast cancer cells so that cancer cells harboring inactivating mutation in BRCA1 have high level of β-hCG." (PMID 34671318, 2021). "Among BRCA mutations identified in breast cancer patients, BRCA1_c.211dupA, BRCA1_c.5266dupC, BRCA2_c.-227-?_7805+?, BRCA2_1310_1313delAAGA, BRCA2_c.1389_1390delAG and BRCA2_c.7654dupA occurred in BCCRs." (PMID 34490083, 2021). "In the cells that are functional for breast cancer susceptibility gene products (BRCA1 and BRCA2), DSBs can be repaired by a process called homologous recombination (HR)." (PMID 34778045, 2021). "Here, the authors perform a case-only genome-wide association study and highlight novel loci associated with breast cancer risk for BRCA1/BRCA2 mutation carriers." (PMID 33597508, 2021). "We explored publicly available familial breast cancer microarray datasets for phenotypes associated with BRCA1- and BRCA2-related breast tumours." (PMID 34287743, 2021). "On average, 10–15% of women diagnosed with breast cancer before 35 years are carriers of pathogenic variants in BRCA1 or BRCA2." (PMID 34529195, 2021). "We found that the PRS is associated with contralateral breast cancer risk in both BRCA1 and BRCA2 heterozygotes of European ancestry and that PRS can be used to refine estimates of contralateral breast cancer risks in these women." (PMID 34113011, 2021). "The overall risk of CBC in women with BRCA1/2 mutations was 2.2%, and the annual risk for breast cancer in patients aged 40 years and younger increased to 2.8%." (PMID 32862296, 2021). "In breast cancer, pathogenic or likely pathogenic germline BRCA1 or BRCA2 variants are present in 6.1% of all cases, and 10–20% of triple-negative breast cancer cases." (PMID 34711195, 2021). "It is understood that 5–10% of breast cancer cases are due to mutations of the breast cancer genes (BRCA1 and 2), with 25% of cases occurring in patients under the age of 30 years." (PMID 34638847, 2021). "Specifically, obesity at menarche or age 21 and lack of physical activity during adolescence was associated with higher risk of early-onset breast cancer in BRCA1/2 mutation carriers." (PMID 33649363, 2021). "The viral vectors have employed to transfer a breast cancer gene BRCA1, as a mutation in BRCA genes is also responsible for breast cancer cases." (PMID 34888205, 2021). "It is predestined that 5- 10 % of breast cancer cases are caused by inherited mutations such as those in the BRCA1 and BRCA2 breast cancer allergy genes." (PMID 34710987, 2021). "Within the studied breast cancer cohort, 13 pathogenic mutations have been identified: 8 in BRCA1 and 5 in BRCA2 genes." (PMID 34490083, 2021). "A range of adipokine-related markers were analyzed in the wildtype and BRCA1-mutated breast cancer cell lines exposed to ADSC-CM." (PMID 34228231, 2021). "Among all breast cancers, 5–10% are hereditary, and BRCA1/2 are widely known as representative genes that can cause hereditary breast and ovarian cancer (HBOC) syndrome." (PMID 34674065, 2021). "For BRCA1 mutation carriers, a decrease in breast cancer risk associated with HRT was found for both women with (HR = 0.52; 95% CI 0.30–0.92) and without RRBSO (HR = 0.29; 95% CI 0.13–0.69)." (PMID 33885953, 2021). "In the present study, we show that histologically normal breast tissue from younger women who are susceptible to breast cancer, as a result of harboring a germline mutation in BRCA1, BRCA2 or PALB2 genes, exhibits hallmarks of accelerated aging." (PMID 35187501, 2021). "While the average woman has a 1 in 8 chance (12%) of developing breast cancer in her lifetime, women with a BRCA1/2 mutation have an estimated 72% risk of being diagnosed with breast cancer." (PMID 35052215, 2021).
breast cancer (continued). "Although germline mutations in BRCA1/2 are generally low, these mutations can confer a lifetime risk of up to 85% of developing breast cancer, with the majority (around 90%) of these tumors being triple-negative." (PMID 34778045, 2021). "Lastly, the use of multi-gene panel testing for hereditary breast cancer risk, not limited to BRCA1/2 pathogenic mutations, is essential to increase the likelihood of detecting an underlying germline genetic component and achieve better PABC patient outcomes." (PMID 34011307, 2021). "The breast cancer susceptibility proteins BRCA1 (also known as FANCS), BRCA2 (FANCD1), and RAD51 (FANCR) and its paralogs, including XRCC2 (FANCU) and XRCC3, all serve a function in homologous recombination repair (HRR)." (PMID 33625522, 2021). "At our hospital, MRI triggered the diagnosis of breast cancer in four cancer-free BRCA1/2 mutation carriers." (PMID 34674065, 2021). "Our study indicates that 10.6% of the breast cancer patients with at least one close relative affected by the disease (until third degree) harbor germline BRCA1/BRCA2 mutations." (PMID 34287479, 2021). "Additional studies are needed to confirm the potential of this strategy and the utility of these markers for future clinical applications of irradiation responsiveness in BRCA1-associated breast cancer." (PMID 33767581, 2021). "In all, 141 women who underwent mastectomy for breast cancer treatment or prevention were included in the study: 74 were positive for BRCA1 mutations and 67 had BRCA2 mutations." (PMID 33649363, 2021). "In Latin America, variants such as BRCA1 185delAG and R1443X are among the 20 most frequent BRCA1 variants reported by the Breast Cancer Information Core database." (PMID 34196900, 2021). "Familial breast cancer accounts for up to 5–10% of diagnosed breast cancer cases, with the most common mutations occurring in the BRCA1/2 genes." (PMID 32524330, 2021). "The most effective breast cancer prevention and management for BRCA1/2-mutation carriers is surgical prevention." (PMID 35008272, 2021). "For example, a G>C mutation in BRCA1 5′-UTR was identified in a highly aggressive sporadic breast cancer and resulted in a defective initiation of BRCA1 protein translation." (PMID 34184986, 2021). "Regardless of how mutations are sequenced, the high prevalence of BRCA1/2 mutations necessitate genetic testing in individuals at risk for ovarian or breast cancer." (PMID 34711195, 2021). "Founder mutations linked to inherited breast cancer have been reported in BRCA1 and BRCA2 genes in different populations." (PMID 35096615, 2021). "In BRCA1-mutated breast cancer cells, increased cytosolic DNA levels and enhanced STING pathway activation have also been observed." (PMID 34067105, 2021). "Primary prevention measures, including prophylactic mastectomy, chemoprevention, and intensive surveillance, can decrease the risk of breast cancer in BRCA1/BRCA2 mutations." (PMID 34206661, 2021). "All studies evaluating the association between BRCA1 methylation status and breast cancer patients’ clinicopathological features were considered for inclusion." (PMID 33808555, 2021). "To investigate the heterogeneity of BRCA1-deficient breast cancers, we firstly referred the human breast cancer cases from public data." (PMID 34815798, 2021). "Patients with a breast cancer diagnosis undergoing extended panel testing were assessed for frequency of actionable variants in breast cancer genes other than BRCA1/2 by histiotype and Manchester score (MS) to reflect a priori BRCA1/2 likelihood." (PMID 34439310, 2021). "The prognosis of breast cancer in BRCA1/2 mutation carriers has been reported extensively, and the results of large-scale cohorts and meta-analyses in this regard are as follows." (PMID 32862296, 2021).
breast cancer (continued). "The PARP inhibitors olaparib and talazoparib were recently FDA approved for use as monotherapy in patients with metastatic germline BRCA1/2-mutated breast cancer based on significant improvement in progression-free survival compared to chemotherapy." (PMID 34465787, 2021). "Phosphorylation of RPS6 has been reported to attenuate DSBs in BRCA1-deficient breast cancer cells both in vitro and in vivo." (PMID 35008473, 2021). "For example, mutations in the single high-penetrance tumor suppressor gene BRCA1/2 are associated with a high relative risk of developing breast cancer." (PMID 34930164, 2021). "Several studies have reported that breast cancers caused by mutations in BRCA1/2 genes have specific characteristics." (PMID 33737705, 2021). "The most commonly occurring mutation in breast cancer patients in our cohort is BRCA1-1687C>T p.(Gln563*), which we found in three individuals." (PMID 34202525, 2021). "Women with the BRCA1 mutation have a 39–46% and 65–85% risk of developing ovarian and breast cancers, respectively." (PMID 35011855, 2021). "We found that Gata3 deficient mammary tumors phenocopied Brca1 deficient tumors in the induction of EMT and promotion of tumorigenesis and progression." (PMID 34373738, 2021). "In breast cancer, for example, cytoplasmic mislocalization of BRCA1 is frequent and has been linked to tumor aggressiveness." (PMID 34003336, 2021). "Though most breast cancer cases are sporadic, 5–10% of cases are hereditary and mostly related to BRCA1 or BRCA2 gene mutations." (PMID 34290354, 2021). "Inherited germline variants in BRCA1 and BRCA2 account for around 2% and 10% of MBC cases, respectively, and the lifetime risk of breast cancer for men harboring BRCA1 and BRCA2 mutations is 1.2% and 6.8%." (PMID 34298749, 2021). "Overall, there is sufficient evidence to conclude breast cancer in patients with BRCA1/2 mutations carries a significantly worse prognosis." (PMID 34070674, 2021). "Olaparib is an oral medication typically used to treat certain advanced ovarian and breast cancers with mutations in BRCA1 or BRCA2 genes." (PMID 33803939, 2021). "The cumulative breast cancer risk for mutation carriers at the age of 70 years is 57% for BRCA1 and 49% for BRCA2 mutation carriers, with a high rate of developing breast cancer." (PMID 34674065, 2021). "Here, we report a rare case of germline BRCA1 mutation-positive breast cancer with chondroid metaplasia." (PMID 33407746, 2021). "We found evidence of association with breast cancer risk for four genes, with estimated adjusted ORs of 5.3 [95% CI: 2.1–16.2] for BRCA1, 4.0 [95% CI: 1.9–9.1] for BRCA2, 3.4 [95% CI: 1.4–8.4] for ATM and 4.3 [95% CI: 1.0–17.0] for PALB2." (PMID 34887416, 2021). "The tumor suppressor gene, BRCA1, is often mutated in the germ line, increasing the risk of basal-type breast cancer significantly." (PMID 34587981, 2021). "To summarize, we have investigated the associations between PRS based on 313 variants with contralateral breast cancer risk in a large international series of BRCA1/2 heterozygotes." (PMID 34113011, 2021). "For instance, poly (ADP-ribose) polymerase (PARP) inhibiting drugs, is used in managing patients with ovarian cancer and breast cancer in cases of pathogenic BRCA-1/2 -gene mutations." (PMID 33916923, 2021). "PARPi are showing promise to treat various cancers with HR deficiencies, particularly breast cancers with germline BRCA1/2 mutations." (PMID 33868586, 2021). "A phase I study of Talazoparib demonstrated promising efficacy and safety profiles in advanced cancers with deleterious BRCA1/2 mutations including breast cancer (NCT01945775)." (PMID 34631532, 2021). "Treatment options for BRCA1-associated breast cancers have been limited by many clinical trial-related hurdles." (PMID 33767581, 2021). "Surprisingly, eIF3e-deficient breast cancer cells are resistant to these drugs, in contrast to BRCA1-deficient cells." (PMID 33868586, 2021).